FGF14 (fibroblast growth factor 14)
Description:
Probably involved in nervous system development and function.
Synonyms: FGF-14; FHF-4; FHF4; SCA27; NYS4; SCA27A; SCA27B
Tractability: Small molecule: a high-quality ligand is known. PROTAC: a small molecule that binds it is known.
Target class: Secreted protein
Gene: Protein-coding gene on chromosome 13 (101,710,804 to 102,402,457, reverse strand). Ensembl gene ENSG00000102466.
Subcellular location: Nucleus
Subcellular location (Human Protein Atlas): Nucleoli fibrillar center
Pathways (Reactome):
Muscle contraction: Phase 0 - rapid depolarisation
Gene Ontology:
Molecular function: protein binding; growth factor activity; sodium channel regulator activity
Biological process: cell-cell signaling; nervous system development; neurogenesis; signal transduction
Cellular component: cytoplasm; nucleus
Genetic constraint (gnomAD): Loss-of-function variants: 4 observed, 19 expected, observed/expected ratio (o/e) 0.21, 90% interval 0.1 to 0.48. The upper end of that interval is the gene's LOEUF score, 0.48, which puts it in group 2 of 6, group 1 being the genes least tolerant of losing a copy. Missense variants: 195 observed, 279.33 expected, observed/expected ratio (o/e) 0.7, 90% interval 0.62 to 0.79. Synonymous variants: 123 observed, 106.47 expected, observed/expected ratio (o/e) 1.16, 90% interval 1 to 1.34.
Homologues: Orthologues: pig FGF14 (99% identical), mouse Fgf14 (99% identical), zebrafish fgf14 (90% identical), chimpanzee FGF14 (80% identical), macaque FGF14 (80% identical), guinea pig FGF14 (80% identical), dog FGF14 (79% identical), rabbit FGF14 (79% identical), rat Fgf14 (79% identical), tropical clawed frog fgf14 (76% identical). Paralogues in human: FGF13 (58% identical), FGF12 (54% identical), FGF11 (50% identical), FGF20 (26% identical), FGF9 (25% identical), FGF3 (23% identical), FGF16 (22% identical), FGF4 (22% identical), FGF5 (22% identical), FGF1 (21% identical), FGF10 (21% identical), FGF6 (21% identical), and 9 more.
Diseases named in the same sentence as FGF14 in open-access papers:
FGF14 is named in the same sentence as 111 diseases in open-access papers, as found by Europe PMC text mining. Sharing a sentence is not in itself a finding about the gene and the disease. The quoted sentences say what the papers report.
Ataxia (56 papers, 2009 to 2026). Ataxia refers to impaired coordination of voluntary muscle movement. "In conclusion, we have identified a pathogenic GAA expansion in intron 1 of FGF14 in 65.2% of an unsolved adult‐onset ataxia cohort in the Care4Rare research program through a combination of molecular tools." (PMID 40191983, 2025). "Restoration of FGF14 expression in homozygous knockout mice via viral delivery reversed ataxia and normalized Purkinje cell firing, demonstrating a causal link." (PMID 41099962, 2025). "FGF14-deficient (homozygous knock-out) mice exhibit ataxia and paroxysmal dyskinesias, which are associated with reduced NaV1.6 expression at the axonal initial segment and impaired Purkinje cell excitability." (PMID 41099962, 2025). "FGF14-deficient mice recapitulated symptoms of ataxia and present with a paroxysmal hyperkinetic movement disorder." (PMID 41099962, 2025). "Spinocerebellar ataxia 27 A (SCA27A) is a form of progressive cerebellar ataxia due to pathogenic variants in the Fibroblast Growth Factor 14 (FGF14) gene." (PMID 41099962, 2025). "Given our results and existing research, we propose including fibroblast growth factor 14 GAA repeat expansion testing as a first-tier genetic diagnostic approach for patients with late-onset cerebellar ataxia." (PMID 39801711, 2025). "Whilst spinocerebellar ataxia is the most typical clinical phenotype of FGF14 pathogenic variants, some patients show episodic symptoms leading to alternate classifications of episodic ataxia or paroxysmal non-kinesigenic dyskinesia." (PMID 41099962, 2025). "Spinocerebellar ataxia type 27B (SCA27B, MIM: 620174) is a recently established late-onset cerebellar ataxia associated with a pure GAA repeat expansion exceeding 250 repeat units in intron 1 of the fibroblast growth factor 14 gene (FGF14)." (PMID 39604554, 2025). "The 802 control subjects showed an overall different distribution of FGF14 alleles compared to patients with ataxia, especially when considering only the larger allele (Mann-Whitney, p = 9.6e-6)." (PMID 39227614, 2024). "The current OMIM nomenclature for the FGF14 mutation-associated ataxia is SCA27 A, and the GAA repeat expansion-related disorder is SCA27B." (PMID 38911333, 2024). "In this study, we identify FGF14 repeat expansions as the most frequently missed genetic cause of cerebellar ataxia in two cohorts of patients, one with available genome data, and the other one with inconclusive diagnostic analyses." (PMID 39227614, 2024). "By combining long-range PCR and nanopore sequencing in 169 patients with cerebellar ataxia and 802 controls, we compare FGF14 expansion alleles, including interruptions and flanking regions." (PMID 39227614, 2024). "Intronic FGF14 GAA repeat expansions have recently been found to be a common cause of hereditary ataxia (GAA-FGF14 ataxia; SCA27B)." (PMID 37646005, 2023). "Dominantly inherited GAA repeat expansions in FGF14 are a common cause of spinocerebellar ataxia (GAA-FGF14 ataxia; spinocerebellar ataxia 27B)." (PMID 37322040, 2023). "Spinocerebellar ataxia 27 (SCA 27) is a rare cerebellar ataxia caused by mutations in the fibroblast growth factor 14 (FGF14) gene characterized by postural tremor manifesting in early adulthood and slowly progressive ataxia in later decades." (PMID 36588880, 2022). "Spinocerebellar ataxia 27 (SCA 27) is a rare heredodegenerative disorder caused by mutations in the fibroblast growth factor 14 (FGF14) and characterized by early-onset tremor and progressive ataxia later during the disease course." (PMID 36588880, 2022). "The expression of Nav1.6 is regulated by the fibroblast growth factor 14 (FGF14), which is mainly expressed in the CNS neurons and is associated with spinocerebellar ataxia (SAC27)." (PMID 35326323, 2022). "A role for FGF14 in axonal trafficking and synaptosomal function was suggested in 2002 by observation that Fgf14-deficient mice developed ataxia and a paroxysmal hyperkinetic movement disorder." (PMID 32443735, 2020).
Ataxia (continued). "A larger FGF14 deletion (441 kb) was associated with a severe phenotype that included ataxia, delayed motor milestones, microcephaly, moderate ID, marked dysmorphism and progressive cerebellar atrophy." (PMID 32112487, 2020). "One year later, heterozygous mutations in FGF14 were identified as causative of an autosomal dominant form of spinocerebellar ataxia, successively classified as SCA type 27." (PMID 32443735, 2020). "A previous study revealed that FGF14 regulates spinocerebellar development, the loss of which leads to spinocerebellar ataxia in mice." (PMID 30518868, 2018). "Homozygous Fgf14 deficient mice are viable and anatomically normal but smaller in size, and develop ataxia and paroxysmal dyskinesia by one month of age." (PMID 29253853, 2017). "Mutations of the intracellular fibroblast growth factor FGF14 have been associated with hereditary spinocerebellar ataxia, a debilitating childhood-onset condition characterized by postural tremor, slowly progressive ataxia, and cognitive deficits." (PMID 25191280, 2014). "SCA27 was described in a Dutch family with early onset tremor, dyskinesia, and slowly progressive cerebellar ataxia associated with a mutation in the fibroblast growth factor 14 (FGF14) gene on chromosome 13q34." (PMID 21619691, 2011). "Dentatorubropallidoluysian atrophy (DRPLA) and ataxia associated with fibroblast growth factor 14 (FGF14) mutation are also considered in this group." (PMID 20808545, 2010). "In humans with FGF14 mutations, the ataxia, dyskinesia and tremors may also be episodic and can be triggered by crying, emotional stress and physical exercise." (PMID 29253853, 2017). "In combination with our data showing that FGF14 also regulates presynaptic voltage-gated Ca2+ channels at the cerebellar granule cell to Purkinje cell synapse, these data pinpoint several specific mechanisms by which mutations in FGF14 underlie spinocerebellar ataxia." (PMID 25269146, 2014). "Although FGF14 haploinsufficiency is associated with spinocerebellar ataxia and intrinsic excitability of cerebellar Purkinje neurons is reduced in Fgf14−/− mice, the detailed multifactorial molecular mechanisms by which FGF14 affects neuronal excitability were not previously known." (PMID 25269146, 2014). "Thus, if these variants identified in spinocerebellar ataxia patients are truly associated with disease, our data suggest mechanisms other than FGF14 overexpression." (PMID 25269146, 2014). "Our results may also provide some insight into the more variable phenotypes and decreased penetrance in spinocerebellar ataxia patients with FGF14 haploinsufficiency vs patients with a FGF14 mutation (FGF14bF150S) found in a large Dutch spinocerebellar ataxia kindred." (PMID 25269146, 2014). "Cerebellar features with gait and limb ataxia, nystagmus (gaze-evoked or vertical) and dysarthria are reported in variable proportion in all cases of FGF14 deletion: 75% (24/32) have nystagmus, 46% (15/32) ataxia, of which half (7/32, 21%) are episodic." (PMID 41099962, 2025). "The numbers of GAA repeat units at the upstream end, as defined by the transcription direction of FGF14, were 34 in one ataxia patient, 27 in one MSA patient, and 27 and 31 in two healthy individuals." (PMID 39604554, 2025). "We searched for expanded GAA repeats in intron 1 of FGF14 in undiagnosed ataxia patients and patients with MSA in the Japanese population." (PMID 39604554, 2025). "We envisage that many other diseases affecting the cerebellum such as the recently described FGF14 GAA repeat expansion in late-onset cerebellar ataxia will benefit from investigating patient-derived hCBOs to advance the promise of precision medicine." (PMID 40463008, 2025).
Ataxia (continued). "This study supports the integration of genetic testing for FGF14 expansions in the diagnostic work-up of MSA, particularly for patients with early-onset cerebellar ataxia, parkinsonism and autonomic dysfunction." (PMID 40239008, 2025). "FGF14-related ataxia bears considerable phenotypic variability, including SCA27, episodic ataxia, and GAA repeat expansion associated late-onset cerebellar ataxia (LOCA)." (PMID 38911333, 2024). "GAA expansion >250 within the FGF14 gene accounts for 10 to 61% of unsolved ataxia cases, in different cohorts analyzed in Australia, Europe, and India." (PMID 38391932, 2024). "In the following section, we will discuss SCA27B, due to a STR expansion in FGF14, and ataxia due to a STR expansion in THAP11, proposed as ‘SCA51’." (PMID 38760634, 2024). "Compared with European cohorts of late-onset ataxia in which the frequency of GAA-FGF14 ataxia is 10–18%,1 2 the frequency of 38% observed in this cohort suggests that FGF14 repeat expansions are enriched in patients partially fulfilling criteria for CANVAS." (PMID 37399286, 2024). "In this study, we identify intronic FGF14 AAG expansions (SCA27B) as a major genetic contributor to cerebellar ataxia that had previously been overlooked by short-read technologies." (PMID 39227614, 2024). "Additional cerebellar ocular motor signs were observed in 100% (82/82) and cerebellar ataxia in 43% (35/82) of patients carrying an FGF14 (GAA)≥250 expansion." (PMID 38507876, 2024). "Individuals with pathogenic FGF14 variants manifest EA or develop SCA27, a progressive cerebellar ataxia frequently presenting with nystagmus, tremor, dysarthria, limb ataxia, and variably associated with psychiatric symptoms and cognitive impairment." (PMID 36207621, 2023). "The missense mutation F145S in the Fibroblast Growth Factor 14 (FGF14) causes SCA27 in humans through a dominant negative effect, and FGF14 ablation induces ataxia in mice." (PMID 32300292, 2020). "Nine patients had ataxia, and all affected patients harboured an interstitial deletion of chromosome 13q33.1 encompassing the entire FGF14 and integrin subunit beta like 1 (ITGBL1) genes." (PMID 32112487, 2020). "Mutations in FGF14 gene, coding for Fibroblast Growth Factor 14, underlie SCA27, a late onset, slowly progressing cerebellar ataxia with extrapyramidal features such as postural tremor, head titubation, and parkinsonism." (PMID 32899446, 2020). "Genetic deletion of Fgf14 in Fgf14−/− mice leads to severe ataxia, paroxysmal dystonia, and cognitive impairment associated with deficits in synaptic plasticity in the hippocampus and neuronal excitability in the cerebellum." (PMID 26089778, 2015). "In mice, targeted disruption of FGF14 produces severe ataxia, paroxysmal dystonia, and cognitive impairment, with neurons that exhibit severe impairments in synaptic plasticity and neuronal excitability." (PMID 25191280, 2014). "In the case of spinocerebellar ataxia, our data suggest that FGF14 is a critical regulator of the ability of cerebellar Purkinje neuron NaV channels to support resurgent NaV current and thereby allow Purkinje neurons to fire repetitively." (PMID 25269146, 2014). "In this study, we show that the NaV channel auxiliary subunit FGF14 ‘b’ isoform, a locus for inherited spinocerebellar ataxias, controls resurgent current and repetitive firing in Purkinje neurons." (PMID 25269146, 2014). "Given emerging evidence that repeat expansions in ataxia-associated genes like RFC1 can contribute to atypical or familial forms of Parkinson's disease, we investigated whether FGF14 expansions might play a similar role." (PMID 41327893, 2026). "We used a combination of LR‐PCR utilizing primers flanking the region of interest in the research lab, and flanking‐PCR combined with RP‐PCR through clinical testing, to assess the contribution of the intronic expansion in intron 1 of FGF14 in our cohort of participants with unsolved ataxia." (PMID 40191983, 2025).
Ataxia (continued). "Given emerging evidence that repeat expansions in ataxia-associated genes like RFC1, can contribute to atypical or familial forms of PD, we investigated whether FGF14 expansions might play a similar role." (PMID 40894141, 2025). "The eight remaining individuals (all three with another neurological disorder and five with ataxia) had a larger allele below 670 bp (i.e., ≤ 170 repeats) and were therefore considered negative for FGF14 expansion/SCA27B." (PMID 39227614, 2024). "We discuss genetic forms of ataxia related to recently discovered genes or gene variant types, including STR expansions in RFC1 (CANVAS), FGF14 (SCA27B) and THAP11 (‘SCA51’), as well as discussing SCA4, for which the genetic basis has only recently been discovered." (PMID 38760634, 2024). "Despite analyzing genome data from both family members, no other ataxia-associated variants were identified, suggesting the FGF14 expansion as the primary culprit." (PMID 39227614, 2024). "The existence of at least one large FGF14 AAG allele (PCR fragment size ≥ 700 bp corresponding to a triplet repeat number ≥ 180, see “methods”) was confirmed for 18 of the 26 individuals, all with cerebellar ataxia." (PMID 39227614, 2024). "EA is a clinically heterogeneous disorder characterized by recurrent spells of ataxia lasting minutes to hours which has been associated over time to a number of genes besides CACNA1A and KCNA1 (CACNB4, SLC1A3, FGF14, SLC2A1, ATP1A3, PRRT2) accounting for the majority of cases." (PMID 32823520, 2020). "A microdeletion (95kb) was associated with impaired gait, delayed motor and language development, low IQ and mild dysmorphism, whereas a larger deletion (202 kb), affecting partially both FGF14 and ITGBL1, was associated with ataxia exacerbated by fever, but with normal IQ." (PMID 32112487, 2020). "Of the listed variants, with the exception of the variant in FGF14, no others were associated with a known human disease, mouse model, gene pathway or function related to the ataxia and neurological signs seen in affected sheep." (PMID 29253853, 2017). "Our results demonstrate that genetic deletion of Fgf14 leads to impairment of synaptic transmission at the PF to Purkinje neuron synapse, phenotypes that might contribute to the cerebellar ataxia observed in the SCA27 human disease." (PMID 26089778, 2015). "An ataxia phenotype in Fgf14−/− mice highlights the role of FGF14 in cerebellar physiology and the development of spinocerebellar ataxia type 27 (SCA27) in patients with either FGF14 haploinsufficiency or a dominant negative FGF14 mutation underscores the role of FGF14 in disease." (PMID 25269146, 2014). "Overall, most patients with FGF14 expansion ≥ 250 AAG repeats (33/42; 78.5%) had a highly recognizable phenotype, characterized by the association of slowly progressive cerebellar signs accompanied by episodic symptoms of ataxia and/or downbeat nystagmus (DBN) that often present as first symptoms." (PMID 39227614, 2024). "Although FGF14 has a long-established link with ataxia, with conventional variants (point mutations, insertions and deletions) known to cause the rare SCA27A (formerly SCA27), it has been recently discovered that a STR expansion in intron 1 of FGF14 also results in an AD HCA, SCA27B." (PMID 38760634, 2024). "Moreover, Fgf14 knock-out mice have been found to display ataxia phenotype." (PMID 38391932, 2024). "In conclusion, we showed that FGF14 GAA repeat expansions are a common cause of cerebellar ataxia plus polyneuropathy and/or BVP in patients negative for biallelic RFC1 repeat expansions, thus expanding the phenotypic spectrum of this recently described disorder." (PMID 37399286, 2024). "We first conducted LR-PCR analysis to identify samples that showed LR-PCR products derived from intron 1 of FGF14 with sizes >750 bps in patients with MSA, patients with undiagnosed ataxia, and healthy individuals." (PMID 39604554, 2025).